REN (renin)
Diseases named in the same sentence as REN in open-access papers (continued):
Sharing a sentence is not in itself a finding about the gene and the disease.
endothelial dysfunction (continued). "They promote each other and ultimately promote the progression of atherosclerosis through inflammation, oxidative stress, endothelial dysfunction and renin–angiotensin–aldosterone system activation." (PMID 37131230, 2023). "The renin-angiotensin system’s modulatory role in atherosclerosis and vascular inflammation can also contribute to endothelial dysfunction, thereby enhancing the atherogenic process, with its hyperfunction in animal models also contributing to AD." (PMID 37627038, 2023). "Proposed mechanisms of uric acid and CKD progression induce oxidative stress, renin-angiotensin system activation, renal epithelial-mesenchymal transition and endothelial dysfunction resulting in developing renal arteriolosclerosis and cardiometabolic disease." (PMID 37596359, 2023). "PM2.5 can unbalance the kidney function by accumulation in the kidney tissue, endothelial dysfunction, abnormal renin-angiotensin system, and immune complex deposition." (PMID 36711599, 2023). "Of note, COVID-19, through direct viral invasion, endothelial dysfunction, renin-angiotensin system dysregulation, cytokine storm, microvascular thrombosis, and other systemic effects, can develop AKI." (PMID 37819890, 2023). "In obstructive sleep apnea (OSA) patients, cyclic intermittent hypoxia can trigger endothelial dysfunction and activate the renin-angiotensin and sympathetic systems." (PMID 37416924, 2023). "Sepsis-induced endothelial dysfunction is proposed to cause angiotensin-converting enzyme (ACE) dysfunction and renin–angiotensin–aldosterone system (RAAS) derangement, exacerbating vasodilatory shock and acute kidney injury (AKI)." (PMID 37308975, 2023). "Among these risk factors, obesity plays an important role in inducing IR, activation of the sympathetic nervous system, increased renin-angiotensin-aldosterone system activity, and endothelial dysfunction." (PMID 38111445, 2023). "Hereditary genes, aberrant sympathetic and renin-angiotensin-aldosterone system activation, endothelial dysfunction, decreased arterial compliance, and increased systemic vascular resistance all contribute to the pathogenesis of resistant hypertension." (PMID 37334401, 2023). "For obesity-related kidney diseases, mechanisms include activation of the renin–angiotensin–aldosterone system, systemic inflammation, endothelial dysfunction, adipokine release, insulin resistance, and hypertension." (PMID 37990049, 2023). "It reduces sympathetic nerve activity, antagonizes the renin–angiotensin–aldosterone system, attenuates inflammatory responses and oxidative stress, and improves endothelial dysfunction and vascular remodeling." (PMID 36814188, 2023). "We have also explored the underlying mechanisms involved in resistant hypertension, including alterations in the renin-angiotensin-aldosterone system, sympathetic nervous system activation, and endothelial dysfunction." (PMID 37416924, 2023). "IR can mediate myocardial damage through a variety of pathways, such as endothelial dysfunction, abnormal fatty acid metabolism, production of glycosylated end-products and free radicals, and overactivation of the renin–angiotensin system." (PMID 37420232, 2023). "We have previously reported that the renin–angiotensin system in leukocytes plays a pivotal role in the development of endothelial dysfunction with high FFA levels." (PMID 36836015, 2023). "CKD causes an increase in blood pressure by enhancing the sympathetic tone, increasing arterial stiffness, endothelial dysfunction, rising salt sensitivity, and increasing the Renin-angiotensin-aldosterone system (RAAS)." (PMID 37355590, 2023). "This increase causes hemodynamic effects on the organism (increased oxidative stress, endothelial dysfunction and activation of the renin–angiotensin–aldosterone system) and contributes to the BP increase." (PMID 37324619, 2023). "Hormonal changes act on the renin-angiotensin axis producing impaired vascular reactivity and endothelial dysfunction." (PMID 37685272, 2023).
endothelial dysfunction (continued). "Hyperglycemia activates renin–angiotensin–aldosterone system (RAAS) and cytokines, which cause endothelial dysfunction and vasospasm." (PMID 37438747, 2023). "Increased glomerular pressure, along with oxidative stress, inflammation, and renin–angiotensin–aldosterone system (RAAS) activation, causes endothelial dysfunction and increases the risk of proteinuria." (PMID 36235692, 2022). "It has been established that there is an enhanced inflammation and oxidative stress, activated renin-angiotensin system, and endothelial dysfunction in DKD status." (PMID 35938702, 2022). "Sympathetic overdrive, endothelial dysfunction, and renin–angiotensin–aldosterone system activation are considered the most important pathogenetic mechanisms for the elevation of blood pressure during the night." (PMID 36140272, 2022). "Then, the virus spreads to the pulmonary blood circulation, and the binding of SARS-CoV-2 to ACE2 from endothelial cells in more distant well-ventilated areas produces an imbalance of the renin–angiotensin system and endothelial dysfunction." (PMID 34980198, 2022). "Second, serum UA is regarded as a sign of metabolic changes related to oxidative stress, endothelial dysfunction, and activation of the renin-angiotensin system." (PMID 35155496, 2022). "A few pathophysiological mechanisms have been suggested to participate in it, such as elevated sympathetic nervous system activity, renin-angiotensin aldosterone system activity, endothelial dysfunction, inflammation, and metabolic dysregulation." (PMID 36545020, 2022). "SGLT2i have been noted to induce osmotic diuresis and natriuresis, improve arterial stiffness, reduce sympathetic activity, suppress the renal renin-angiotensin system, decrease oxidative stress, and potentially improve endothelial dysfunction." (PMID 35879763, 2022). "We focused on the role of the inflammatory response, renin-angiotensin system and endothelial dysfunction in the development of atherosclerosis in patients with COVID-19." (PMID 36626452, 2022). "The proposed SARS-CoV-2-induced dysregulation of the renin-angiotensin-aldosterone (RAAS) system results in endothelial dysfunction and microvascular thrombosis." (PMID 35885894, 2022). "Because Classic phenotype primarily affects vascular endothelial cells, endothelial dysfunction can lead to an impaired renal microcirculation resulting in increased active renin levels." (PMID 34751898, 2022). "Oxidative stress and the activation of the renin-angiotensin system in human vascular endothelial cells is the main mechanism of SUA-induced endothelial dysfunction." (PMID 35811724, 2022). "In turn, inhibition of the renin-angiotensin system prevents acute endothelial dysfunction induced by free fatty acids." (PMID 35163232, 2022). "Particularly, the activated renin–angiotensin–aldosterone system, chronic inflammation, endothelial dysfunction, and hypercoagulation state play an important role in the underlying mechanism linking COVID-19 to DKD." (PMID 36341356, 2022). "Factors, such as the activation of renin-angiotensin and sympathetic system, as well as endothelial dysfunction, promote oxidative stress and subsequent cardiovascular tissue injury." (PMID 36299874, 2022). "Vitamin D can reduce endothelial dysfunction by suppressing renin production, which reduces activity of the renin–angiotensin–aldosterone system and increases expression of endothelial NO synthase (eNOS)." (PMID 36145186, 2022). "Adipokines are involved in microvascular injury and kidney damage by mediating endothelial dysfunction, inducing oxidative stress, inflammation, activation of the renin–angiotensin–aldosterone system and endoplasmic reticulum stress." (PMID 35209907, 2022). "Abundant evidence has indicated that hyperuricemia independently predicts the incidence and development of CKD through endothelial dysfunction, activation of the renin–angiotensin system, and enhances oxidative stress within the cell." (PMID 35461256, 2022).
endothelial dysfunction (continued). "Hyperuricemia also induces renal vasoconstriction via inflammation, endothelial dysfunction, and renin–angiotensin system activation similar to its effect on cardiovascular outcomes." (PMID 35885024, 2022). "Some other studies found that high SUA can activate the chronic inflammatory response, oxidative stress, induce endothelial dysfunction and activate the renin angiotensin aldosterone system to further aggravate the degree of insulin resistance." (PMID 35794651, 2022). "We evaluated CysLT at admission and during hospitalization and their correlation with endothelial dysfunction, inflammation, oxidative stress, the renin–angiotensin–aldosterone system, and cardiac, renal, respiratory, and hepatic parameters in SS patients." (PMID 36359365, 2022). "Hyperglycemia and insulin resistance lead to microvascular endothelial dysfunction, impaired cardiac metabolism, increased myocardial fibrosis, oxidative stress, and activation of the renin–angiotensin system and sympathetic nervous system." (PMID 34356208, 2021). "Proposed mechanisms underlying intracranial hemorrhage in COVID-19 include coagulation abnormalities, endothelial dysfunction, dysregulation of the renin-angiotensin system, and disruption of cerebral blood flow autoregulation." (PMID 34642371, 2021). "Other pathogenic mechanisms, including sympathetic nervous system activation, the renin‐angiotensin‐aldosterone system, arterial stiffness, and endothelial dysfunction, also contributed to BP modulation." (PMID 34263995, 2021). "UA significantly increased the production of reactive oxygen species, facilitated the activation of the renin-angiotensin system, and induced endothelial dysfunction." (PMID 34218791, 2021). "Nevertheless, high uric acid concentrations can have direct pathophysiological effects, including increased oxidative stress, inflammation, endothelial dysfunction, activation of the renin–angiotensin–aldosterone system, and insulin resistance." (PMID 34025575, 2021). "Activation of renin–angiotensin system, aortic inflammation, and vascular metalloproteinase activity lead to changes in the extracellular matrix and endothelial dysfunction, which thereby increase arterial stiffness." (PMID 34120562, 2021). "Hyperuricemia has been shown to stimulate the renin-angiotensin system, inhibit neuronal nitric oxide synthase and induce endothelial dysfunction." (PMID 34722684, 2021). "These hyperinsuliemia, insulin resistance and finally upregulated renin-angiotensin system, are thought to contribute to endothelial dysfunction, atherosclerosis and CVD." (PMID 34746061, 2021). "HTN and T2DM are closely interlinked due to similar risk factors including obesity, dyslipidemia, insulin resistance, endothelial dysfunction, vascular inflammation, atherosclerosis, and sequential inappropriate activation of renin-angiotensin system, etc.." (PMID 34209622, 2021). "Increased production of thromboxane (TxA2) is observed in aldosterone-induced endothelial dysfunction, suggesting an association between the cyclooxygenase (COX) pathway and the renin-angiotensin-aldosterone (RAA) system." (PMID 34945112, 2021). "This is accompanied by chronic inflammation, oxidative stress, endothelial dysfunction, and untoward activation of renin-angiotensin-aldosterone systems and the sympathetic nervous system." (PMID 34684374, 2021). "Endothelial dysfunction, renin-angiotensin aldosterone system, ion transport, and decrease in estrogen levels are known components that contribute to salt-sensitive hypertension." (PMID 33549053, 2021). "High production of ROS in DM plays an essential role in endothelial dysfunction through the inactivation of nitrite oxide (NO) and activation of renin-angiotensin-system (RAS)." (PMID 34326888, 2021).
endothelial dysfunction (continued). "Increased RAS activity (renin), endothelial dysfunction (vWF), coagulation parameters (D-dimer, prothrombin fragment F1,2) and inflammation (CRP, IL-6) were significantly altered in COVID patients and followed similar trends from mild-COVID to ARDS-COVID." (PMID 34945736, 2021). "Oxidative stress, inflammation, activation of the renin-angiotensin system, endothelial dysfunction, abnormal calcium-phosphate metabolism, and elevation of lipoprotein(a) are among the feasible mechanisms connecting CKD and PAD incidence." (PMID 33639945, 2021). "Oxidative stress, endothelial dysfunction, and activation of renin-angiotensin system lead to kidney dysfunction." (PMID 34633265, 2021). "SUA leads to the oxidative stress and endothelial dysfunction with activation of the renin-angiotensin-aldosterone system, besides inducing the activation of inflammatory pathways." (PMID 34530770, 2021). "The major pathways involved in the pathogenesis of COVID-19 and Cardiovascular disease include ACE 2 receptor invasion and Renin-Angiotensin Signaling; immune dysregulation, inflammation, oxidative stress, endothelial dysfunction, and coagulopathy." (PMID 33282075, 2020). "Several mechanisms have been discussed to contribute to the excessive increase in BP during exercise, including aortic distensibility, endothelial dysfunction, and increased activation of the renin–angiotensin–aldosterone system." (PMID 32588193, 2020). "The possible pathophysiologic mechanisms involve endothelial dysfunction, vasoconstriction, sympathetic activation, and activation of the renin-angiotensin-aldosterone system." (PMID 33005509, 2020). "This hypertensive response is complex, however, often accompanied by endothelial dysfunction, smooth muscle cell phenotypic modulation, and inflammatory cell infiltration as well as global effects on the central nervous and renin-angiotensin systems." (PMID 33079926, 2020). "We explore commonalities in the underlying pathophysiology observed in COVID-19 and cardio-oncology, including inflammation, cytokine release, the renin-angiotensin-aldosterone-system, coagulopathy, microthrombosis, and endothelial dysfunction." (PMID 33344513, 2020). "Statins and inhibitors of the renin-angiotensin axis have demonstrated the capability to prevent eNOS uncoupling, improve NO bioavailability and attenuate endothelial dysfunction." (PMID 32635218, 2020). "Experimental studies in mice, rats, and swine have shown vitamin D to have several cardioprotective effects, including decreases in renin‐angiotensin activation, myocardial hypertrophy, endothelial dysfunction, and pro‐inflammatory cytokines." (PMID 32557856, 2020). "Uric acid induces hyalinosis and thickening of preglomerular arterioles, and it promotes endothelial dysfunction, glomerular hypertrophy, and activation of the renin-angiotensin system." (PMID 31110596, 2019). "The uric acid at high levels has the potential to induce renal injury through different mechanisms such as renal vasoconstriction mediated by endothelial dysfunction, inflammation, activation of the renin-angiotensin system, and afferent renal arteriolopathy." (PMID 31110596, 2019). "Possible reasons include; salt retention and abnormal renin-angiotensin stimulation, sympathetic overdrive and endothelial dysfunction via reduced nitric oxide bioavailability." (PMID 29609642, 2018). "The pathophysiology of HTN in OSA is complex and dependent on various factors such as sympathetic tone, renin-angiotensin-aldosterone system, endothelial dysfunction, and altered baroreceptor reflexes." (PMID 29147581, 2017). "Hyperuricemia, the key underlying abnormality in gout, impairs nitric oxide production and activates the renin-angiotensin system, leading to endothelial dysfunction, which also contributes to increased blood pressure." (PMID 29041963, 2017).
endothelial dysfunction (continued). "Various factors are reported to increase renal vascular resistance following IR, including activation of tubuloglomerular feedback, sympathetic nervous system, renin-angiotensin system, prostaglandins, platelet-activating factor and endothelial dysfunction." (PMID 29155898, 2017). "The mainmechanisms of increased BP in patients with OSA are increased sympathetic activity,renin-angiotensin system dysfunction, endothelial dysfunction, hypoxemia, anddisruption of normal sleep." (PMID 28876375, 2017). "A systemic proinflammatory state in combination with activation of the renin–angiotensin system and decreased nitric oxide bioavailability as found in obesity leads to endothelial dysfunction." (PMID 28615046, 2017). "Third, visceral obesity and associated insulin resistance lead to hyperinsulinemia and activate the renin-angiotensin system, which can lead to glomerular hypertension, endothelial dysfunction, vasoconstriction, and matrix proliferation and expansion." (PMID 26902522, 2017). "Recent studies have demonstrated that elevated RDW was associated with renin–angiotensin–aldosterone system (RAAS) activation, autonomic regulation, malnutrition, and endothelial dysfunction." (PMID 29237417, 2017). "Systemic inflammation causes the reduced production of nitric oxide (NO) and increased activity of the renin-angiotensin system, leading to endothelial dysfunction." (PMID 27801876, 2016). "On the other hand, hyperuricemia induces renal injury via a crystal-independent mechanism involving renal vasoconstriction mediated by endothelial dysfunction and activation of renin-angiotensin system." (PMID 26842652, 2016). "In animals fed with oxonic acid, an uricase inhibitor, elevated uric acid levels promoted chronic kidney disease via endothelial dysfunction, local activation of the renin–angiotensin system, oxidative stress, and preglomerular arteriolar damage." (PMID 26029914, 2015). "Excess UA is closely related to components of metabolic syndrome, endothelial dysfunction, inflammation, oxidative stress and activated renin-angiotensin-aldosterone system in general population and patients with CKD." (PMID 24416142, 2014). "This imbalance can induce changes in the cardiovascular system, resulting in adrenergic vasoconstriction, increased cardiac output and activation of the renin-angiotensin system, leading to endothelial dysfunction and vasoconstriction." (PMID 23029413, 2012). "Obesity-induced inflammation, oxidative stress, mitochondrial dysfunction, gut dysbiosis, renin-angiotensin-aldosterone system overactivity, and endothelial dysfunction are further exacerbated by the development of NAFLD, ultimately accelerating ASCVD progression." (PMID 41536939, 2026). "Therefore, Nrf2 activators can attenuate endothelial dysfunction, renin–angiotensin system dysregulation, immune thrombosis, and coagulopathy." (PMID 40733716, 2025). "Diastolic dysfunction may be related to several factors such as endothelial dysfunction, oxidative stress, and inflammation, renin-angiotensin-aldosterone system dysregulation, impaired calcium handling." (PMID 40364153, 2025). "Other mechanisms may include hyperactivity of the renin-angiotensin-aldosterone system, pro-inflammatory responses, and endothelial dysfunction." (PMID 39897192, 2025). "On the one hand, the renin–angiotensin system could contribute to renal vasoconstriction; on the other hand, this system could promote endothelial dysfunction, cardiac fibrosis, ventricular dysfunction, and heart failure." (PMID 41156029, 2025). "The AGT M235T polymorphism may contribute to IHD risk by increasing angiotensinogen levels, enhancing the renin-angiotensin-aldosterone system (RAAS), and promoting endothelial dysfunction and vascular remodeling." (PMID 40717713, 2025). "In addition, miR-122 causes angiotensin II-induced endothelial dysfunction and vascular fibrosis by targeting sirtuin 6 (SIRT6), a negative regulator of the renin-angiotensin system." (PMID 40565979, 2025).